TECTA (tectorin alpha)
Description:
One of the major non-collagenous components of the tectorial membrane (By similarity). The tectorial membrane is an extracellular matrix of the inner ear that covers the neuroepithelium of the cochlea and contacts the stereocilia bundles of specialized sensory hair cells. Sound induces movement of these hair cells relative to the tectorial membrane, deflects the stereocilia and leads to fluctuations in hair-cell membrane potential, transducing sound into electrical signals.
Synonyms: DFNA12; DFNA8; DFNB21
Tractability: Antibody: UniProt places it where antibodies can reach, with high confidence; its Gene Ontology location is reachable by antibodies, with high confidence; UniProt predicts a signal peptide or a membrane-spanning region. PROTAC: ubiquitination databases record sites on it.
Gene: Protein-coding gene on chromosome 11 (121,101,243 to 121,191,490, forward strand). Ensembl gene ENSG00000109927.
Subcellular location: Cell membrane; Secreted, extracellular space, extracellular matrix
Pathways (Reactome):
Metabolism of proteins: Post-translational modification: synthesis of GPI-anchored proteins
Gene Ontology:
Molecular function: extracellular matrix structural constituent
Biological process: sensory perception of sound; cell-matrix adhesion
Cellular component: extracellular exosome; extracellular matrix; extracellular region; plasma membrane
Genetic constraint (gnomAD): Loss-of-function variants: 127 observed, 222.73 expected, observed/expected ratio (o/e) 0.57, 90% interval 0.49 to 0.66. The upper end of that interval is the gene's LOEUF score, 0.66, which puts it in group 2 of 6, group 1 being the genes least tolerant of losing a copy. Missense variants: 2,547 observed, 2,911 expected, observed/expected ratio (o/e) 0.87, 90% interval 0.85 to 0.9. Synonymous variants: 1,085 observed, 1,167.2 expected, observed/expected ratio (o/e) 0.93, 90% interval 0.88 to 0.98.
Gene-disease validity (ClinGen):
ClinGen rates the evidence that TECTA causes each of these diseases.
nonsyndromic genetic hearing loss (autosomal dominant; autosomal recessive): Definitive. A disease characterized by hearing loss that is not part of a larger syndrome.
Homologues: Orthologues: chimpanzee TECTA (99% identical), macaque TBCEL (98% identical), mouse Tecta (96% identical), dog TECTA (96% identical), rabbit TECTA (96% identical), rat Tecta (95% identical), pig TECTA (95% identical), guinea pig TECTA (94% identical), tropical clawed frog tecta (79% identical), zebrafish tecta (60% identical). Paralogues in human: FCGBP (27% identical), MUC5AC (19% identical), MUC5B (19% identical), OTOG (16% identical), VWF (16% identical), OTOGL (16% identical), MUC6 (15% identical), ZAN (15% identical), MUC2 (15% identical), MUC19 (15% identical), KCP (12% identical), CRIM1 (8% identical), and 7 more.